IL6R (interleukin 6 receptor)
Diseases named in the same sentence as IL6R in open-access papers (continued):
Sharing a sentence is not in itself a finding about the gene and the disease.
osteosarcoma (9 papers, 2012 to 2025). A usually aggressive malignant bone-forming mesenchymal neoplasm, predominantly affecting adolescents and young adults. "Moreover, by regulating the miR-520a-3p/IL6R axis in osteosarcoma, LINC01116 promotes cell viability and migration." (PMID 33762953, 2021). "The authors demonstrated that the inhibition of IL6R signaling by tocilizumab prevented osteosarcoma metastasis formation and suggested that TGFβ-blocking agents could be tested as new therapeutic options for osteosarcoma patients." (PMID 33869035, 2021). "In osteosarcoma, our previous study found that LINC01116 promotes cancer development by regulating the expression of miR-520a-3p and IL6R." (PMID 33762953, 2021). "In the present study, we found that FBXO2 can affect the stability of IL-6R, and knocking out FBXO2 can inhibit the proliferation of osteosarcoma cells both in vitro and in vivo." (PMID 32549792, 2020). "Recent studies on osteosarcoma involving the LCP1 gene (also known as actin-bundling protein L-plastin or LPL), have shown that the aberrant expression of LCP1 gene activates the JAK2/STAT3 signaling pathway, linking IL-6, IL-6R, and LCP1 in the context of tumor progression." (PMID 40759647, 2025).
systemic juvenile idiopathic arthritis (9 papers, 2016 to 2025). "Intriguingly, the mechanistic analysis suggests that both biological drug strategies (IL-1 and IL6R blockade) would be equally related to general Still’s disease pathophysiology, as well as the systemic and the rheumatic component." (PMID 33892792, 2021). "Due to the autoinflammatory nature of Still’s disease, deeper analysis on how IL-1 vs. IL6R blockers may affect the innate immune system was performed by modeling their mechanisms of action in detail, which were later biologically validated with expression data." (PMID 33892792, 2021).
eczema (8 papers, 2019 to 2024). "Filaggrin (FLG) variants are specifically associated with eczema, whereas other genome-wide significant loci such as IL6R show almost perfect symmetry in association with each of the 3 diseases." (PMID 32642022, 2020). "We provide evidence from the conservative MR and moloc analyses that supports a causal role between soluble IL-6R and eczema/dermatitis." (PMID 31276585, 2019). "Evidence of colocalization for the association between soluble IL-6R and eczema/dermatitis was observed in three tissue types, most strongly in whole blood (PPA = 99.52%), which may help shed light on the pleiotropic effects observed at this locus." (PMID 31276585, 2019). "However, the associations between soluble IL-6R variation and eczema/dermatitis or IL-18 and IBD within human populations are less well understood." (PMID 31276585, 2019). "Some of the underlying genes, such as FLG, IL6R, CARD11, and IL2RA, were also reported in GWAS on eczema, others were located in or near eczema susceptibility loci." (PMID 38835414, 2023). "Through the moloc analysis, we showed that eczema/dermatitis was likely to be driven by IL-6R expression in T cells." (PMID 31276585, 2019). "Using this framework, we found evidence to support causal relationships between levels of circulating IL-18 and IBD, as well as eczema/dermatitis, circulating soluble IL-6R and eczema/dermatitis and circulating IL-2Rα and MS, amongst others." (PMID 31276585, 2019). "Additionally, we found evidence of a T cell-specific role in the disease pathways of eczema/dermatitis (PPAabc = 91.15%) driven by soluble IL-6R." (PMID 31276585, 2019).
gastric adenocarcinoma (8 papers, 2012 to 2021). "Previous reports indicated that miR-23a/24/27a functions as a growth-promoting and antiapoptotic factor in HCC cells, while miR-23a-3p was also shown to promote the growth of gastric adenocarcinoma cells and downregulate an interleukin-6 receptor." (PMID 26110567, 2015). "As one of the most famous members of the miRNA-cluster, miR-23a has been shown to promote the growth of gastric adenocarcinoma cells by targeting the interleukin-6 receptor." (PMID 24520301, 2014). "Furthermore, miR-23a/24/27a functioned as a growth-promoting and anti-apoptotic factor in HCC cells, while miR-23a was also shown to promote the growth of gastric adenocarcinoma cells and downregulate interleukin-6 receptor." (PMID 22752005, 2012). "One study performed a retrospective analysis of bazedoxifene, an inhibitor of the IL-6/IL-6R/GP130 complex, in patients with pancreatic (n = 5) or gastric adenocarcinoma (n = 2), showing biological tumor marker reduction in 80% and disease regression on PET-CT in 60% of cases." (PMID 34138876, 2021). "While IL-6 can induce miR-23a in hepatocytes, and miR-23a targets IL-6R in gastric adenocarcinoma cells, to our knowledge, there is no information regarding the regulation of IL-6 by miR-23a." (PMID 24143215, 2013).
liver fibrosis (8 papers, 2017 to 2025). "This study investigated the expression and regulation of IL-6R in hepatitis B-associated moderate hepatic fibrosis and cirrhosis." (PMID 28953986, 2017). "However, the control of IL-6R in hepatitis B-associated liver fibrosis and cirrhosis and the regulatory pathway of IL-6R in this process has yet to be fully understood." (PMID 28953986, 2017). "In this study, we investigated the expression of IL-6R as well as its possible regulator miR-30b in hepatitis B patients with moderate liver fibrosis or moderate liver cirrhosis." (PMID 28953986, 2017). "Il-6r mRNA expression was significantly increased in hepatic cirrhosis samples compared with hepatic fibrosis samples (P<0.05), suggesting that IL-6R is elevated in liver cirrhosis patients." (PMID 28953986, 2017). "Compared with the hepatic fibrosis group, IL-6R was significantly upregulated at both mRNA and protein levels in liver tissues, PBMs and serum samples from the hepatic cirrhosis group (P<0.05)." (PMID 28953986, 2017). "In this study, real-time PCR, western blot and ELISA were used to detect the expression of IL-6R in liver tissues, peripheral blood monocytes (PBMs) and serum from hepatitis B patients with moderate hepatic fibrosis or moderate hepatic cirrhosis." (PMID 28953986, 2017). "Further studies are needed to investigate the role and mechanism of IL-6R and miR-30b in the transition of liver fibrosis to cirrhosis." (PMID 28953986, 2017). "Collectively, these findings underscore the importance of understanding IL-6’s tissue-specific roles and suggest that while IL-6R antagonists hold promises for modulating immune-driven fibrotic pathways, their translation into therapies for liver fibrosis must be approached with caution." (PMID 40693271, 2025). "Moreover, myeloid-specific IL-6Rα knockout mice (Il6raMye-/-) and IL-6-silenced mice subjected to high-fat diets exhibited reduced inflammation but increased liver fibrosis, further highlighting the complex and sometimes contradictory role of IL-6 in fibrosis." (PMID 39995661, 2025). "As expected, IL-6R protein level was also upregulated in patients with cirrhosis compared with patients with hepatic fibrosis (P<0.05), indicating that upregulated IL-6R expression may regulate the development of hepatic cirrhosis in hepatitis B patients." (PMID 28953986, 2017). "However, the role and mechanism of IL-6R upregulation in the transition of liver fibrosis to cirrhosis still needs further investigation." (PMID 28953986, 2017). "In addition, the Ingenuity Pathway Analysis predicted the impact on tryptophan, isoleucine, and valine pathways, hematopoiesis from pluripotent stem cells, hepatic fibrosis, retinoid X receptor activation, endocytosis, and the complement system by IL-6/IL-6R treatment." (PMID 34795667, 2021). "IL-6 through its receptors of IL-6R (CD236) and glycoprotein 130 can activate the Janus kinases (JAK) and signal transducer and activator of transcription 3 (STAT3) signaling, enhancing liver fibrosis." (PMID 37679346, 2023). "Research interests in targeting IL-6R have shown clinical efficacy in various inflammatory diseases; however, its role in liver fibrosis remains complex and not fully elucidated." (PMID 40693271, 2025).
lymphoma (8 papers, 2014 to 2023). A malignant (clonal) proliferation of B- lymphocytes or T- lymphocytes which involves the lymph nodes, bone marrow and/or extranodal sites. "In stratified analysis by tumor subtype, we did not determine any significant associations between EVs bearing PD-L1, CD40, FasL, IL-6Rα, B7-H3, CD40L, ICAM-1 or CD20 with DLBCL, BL, and NOS lymphoma subtypes." (PMID 37809067, 2023). "Primary DLBCL cells and DLBCL cell lines expressing IL‐6R engraft and form orthotopic lymphomas in humanized mice that ectopically produce human IL‐6, and in mice reconstituted with a human immune system." (PMID 31515941, 2019). "CD40, TNF-RII or IL-6Rα on EVs may facilitate communication between lymphoma cells and distant immune cells of the tumor microenvironment." (PMID 35655072, 2022). "The primary lymphoma cells used here express high levels of the IL‐6R α‐chain and of the signaling chain gp130 and are positive for the phosphorylated form of the signal transducer and activator of transcription STAT3, which mediates signal transduction downstream of the IL‐6R heterodimer." (PMID 31515941, 2019). "Anti-IL-6 antibody could abrogate the IL-6/IL-6R axis and promote the apoptosis of lymphoma cells." (PMID 36104733, 2022). "Our results showed that both IL6R (rs2228145) and STAT5B (rs6503691) significantly contributed to the Ann Arbor stages of lymphoma." (PMID 37329186, 2023). "We used this antibody to demonstrate in our lymphoma‐bearing mice that blocking the IL‐6R slows tumor growth and comes with virtually no side effects to the mice." (PMID 31515941, 2019). "The aptamer photosensitizer conjugate described in this study could possibly target a broad range of malignant cell types that are accessible to the irradiation of PDT without prior surgical action, as the aptamer target IL6R is present on B- and T-lymphoma cells." (PMID 24481022, 2014).
neutropenia (8 papers, 2014 to 2025). A decrease in the number of neutrophils found in the blood. "In the present work, we showed that while the inhibition of IL-6R is associated with neutropenia and monocytosis, different anti-TNFα therapies cause a wide spectrum of changes in hematological variables." (PMID 35651659, 2022). "Besides, this study sustained that TCZ monotherapy causes lipid elevations and reversible neutropenia linked to IL-6R inhibition." (PMID 40066438, 2025). "A majority of patients in all treatment groups experienced TEAEs, with neutropenia more frequently reported in patients who received sarilumab, as expected due to the known PD effect of IL-6R inhibition on neutrophil counts." (PMID 37840134, 2023). "A few biologic drugs such as TNF-α, IL6R, and CD20 inhibitors, can cause complications of neutropenia." (PMID 30884802, 2019). "In contrast, neutropenia occurs relatively frequently during the IL-6R blocker therapy (with a frequency of 29% and 33% in two randomized controlled trials (RCTs), but high-grade neutropenia or significant infectious events are rare." (PMID 24620738, 2014). "Furthermore, the side effects of anti-IL-6 and anti-IL-6R antibody therapy include neutropenia, abnormal liver function, and respiratory infections, including TB." (PMID 37854602, 2023).
pulmonary arterial hypertension (8 papers, 2020 to 2025). Pulmonary arterial hypertension (PAH) is a group of diseases characterized by mean pulmonary artery pressure >20 mmHg and elevated pulmonary arterial resistance leading to right heart failure. "A recent study showed the importance of IL6R and its potential prosurvival effects in pulmonary hypertension under hypoxic conditions." (PMID 34434114, 2021). "The membrane-bound IL-6R was upregulated on SMCs of patients suffering from pulmonary arterial hypertension, and IL-6R trans-signaling critically contributed to pancreatitis-associated lung injury and in infection with L. monocytogenes." (PMID 33392273, 2020). "At present, an open-label study of the IL-6R antagonist tolicizumab for the treatment of pulmonary arterial hypertension (TRANSFORM-UK) is running, and results are expected soon." (PMID 33105588, 2020). "In addition, mice with specific knockout of IL-6R exhibit resistance to hypoxia-induced pulmonary hypertension (HPH)." (PMID 33269111, 2020). "Furthermore, TRP-metabolism was activated in treatment-naïve pulmonary arterial hypertension (PAH) patients, likely mediated through IL-6/IL-6Rα signaling." (PMID 37892130, 2023). "Additionally, a disease–gene association circos plot generated using RAW Graphs 2.0 showed tight linkage of hub DEGs such as DAPK2, DUSP3, IL6R, and UGP2 to cardiovascular comorbidities, including heart failure, diabetic retinopathy, cardiomyopathy, and pulmonary hypertension." (PMID 41262879, 2025).
pulmonary fibrosis (8 papers, 2013 to 2024). Chronic progressive interstitial lung disorder characterized by the replacement of the lung tissue by connective tissue, leading to progressive dyspnea, respiratory failure, or right heart failure. "Tocilizumab, a drug that targets IL-6R, has shown beneficial improvements in skin and pulmonary fibrosis in SSc." (PMID 39086645, 2024). "Production of IL-6 and soluble IL-6R by cultured peripheral blood mononuclear cells were significantly higher in patients with SSc and soluble IL-6R levels significantly correlated with the severity of pulmonary fibrosis in patients with SSc." (PMID 24046769, 2013). "While expression of genes coding for soluble mediators (e.g. cytokines) were unchanged, receptors for several mediators known to participate in lung fibrosis were up-regulated (CCR2, FGFR2, FLT1, IGF1R, IL1R1 and IL6R)." (PMID 23844029, 2013).
respiratory failure (8 papers, 2021 to 2026). The significant impairment of gas exchange within the lungs resulting in hypoxia, hypercarbia, or both, to the extent that organ tissue perfusion is severely compromised. "Despite noninvasive ventilation and intensive immunosuppressive treatment, including high-dose corticosteroids, intravenous immunoglobulin, and an interleukin-6 receptor inhibitor, the patient's condition deteriorated, resulting in respiratory failure and death 12 days after admission." (PMID 41711249, 2026). "However, the effect of anti-IL-6R antibodies on the progression of respiratory failure or mechanical ventilation (either as an individual outcome or as a composite outcome with death) was not reported in this meta-analysis." (PMID 37598275, 2023). "Specific therapies include remdesivir, anti-interleukin-6 receptor antibodies, Janus kinase inhibitors as well as the microtubule disruptor sabizabulin which has shown promising results in a recent phase II clinical trial in reducing mortality and respiratory failure." (PMID 37143130, 2023). "Patients were not eligible if they exhibited respiratory failure requiring invasive mechanical ventilation, septic shock, or multiple organ dysfunction at enrollment or received cytokine inhibitory therapy (targeting IL-6, IL-6R, IL-1, or Janus kinase)." (PMID 37606044, 2023).
systemic lupus erythematosus (8 papers, 2015 to 2025). An autoimmune multi-organ disease typically associated with vasculopathy and autoantibody production. "Inhibition of IL‐6R signalling might be helpful in lupus cases with predominant skin involvement, but combinatorial treatment might be required to restrain autoantibodies." (PMID 26739431, 2016).
Alzheimer disease (7 papers, 2016 to 2024). A progressive, neurodegenerative disease characterized by loss of function and death of nerve cells in several areas of the brain leading to loss of cognitive function such as memory and language. "In the central nervous system, IL-6 and IL-6R promote chronic inflammation and contribute to neurodegeneration and the development of Alzheimer's disease." (PMID 27119508, 2016).
bladder cancer (7 papers, 2019 to 2025). "In bladder cancer, miR-125b functions as a tumor suppressor by post-transcriptionally regulating IL-6R and STAT3 through direct interaction with their 3′ untranslated regions (3′-UTRs)." (PMID 41179679, 2025). "We also showed that the IL-6 cytokine was highly expressed by CAFs, and its receptor IL-6R was found on RT4 bladder cancer cells." (PMID 30744595, 2019). "Additionally, studies have confirmed that IL-6 is upregulated in bladder cancer iCAFs, indicating that the expression of IL-6R in bladder cancer cells is suitable for responding to the IL-6 cytokine secreted by iCAFs." (PMID 38542078, 2024). "CAFs express the IL-6 cytokine, and its receptor IL-6R was found in RT4 bladder cancer cells." (PMID 37880682, 2023). "Hua Wei reported that IL6/IL6R/STAT3 axis is critical for the maintain of the stem-like properties, and blockage of IL6R inhibit the invasion, migration and tumorigenicity of bladder cancer CSCs." (PMID 38462600, 2024).
giant cell arteritis (7 papers, 2012 to 2024). "TCZ, a humanized anti-interleukin-6 receptor monoclonal antibody, given subcutaneously is effective and licensed in giant cell arteritis." (PMID 35126670, 2022).
mastitis (7 papers, 2018 to 2025). Inflammation of breast tissue during lactation or postpartum due to an obstructed duct or infection. "The genes correlated with downregulated SNORA1 (e.g., JAK2 and IL6R) have been shown to stimulate inflammation during subclinical mastitis as discussed in several reviews." (PMID 40936092, 2025). "In the breast tissue of dairy cows with clinical mastitis, the level of DNA methylation in exon 2 of the bovine IL6R gene is up-regulated, and it is speculated that its methylation levels may be a potential biomarker for monitoring dairy cow mastitis." (PMID 37569258, 2023). "The results suggested that the IL6R gene may regulate cattle mastitis by modifying DNA methylation modification." (PMID 37372369, 2023). "Moreover, genome-wide DNA methylation alteration in the format of CmCGG was significantly related to the immune response to S. aureus-induced mastitis, and several genes including IL-6R, TNF, BTK, IL-1R2, and TNFSF8 were identified as potential epigenetic markers of S. aureus mastitis." (PMID 33708235, 2020). "CmCGG DMEGs like IL6R, TNF, BTK, IL1R2, and TNFSF8 enriched in several immune-related GO terms and pathways indicated their important roles in host immune response and their potential as candidate genes for S. aureus mastitis." (PMID 33193625, 2020).
neuromyelitis optica spectrum disorder (7 papers, 2013 to 2025). "Interleukin-6 receptor blockade is effective in reducing the risk of relapses in neuromyelitis optica spectrum disorder (NMOSD)." (PMID 34745082, 2021). "Recently, two case series demonstrated that treatment with anti-IL-6R mAb has positive effects in neuromyelitis optica spectrum disorders in humans, further underlining the relevance of IL-6 in pathogenesis of CNS demyelinating disorders." (PMID 24155968, 2013). "Interleukin-6-receptor inhibitors like Tocilizumab and Satralizumab are showing promising results in the treatment of Neuromyelitis Optica spectrum disorder (NMOSD)." (PMID 34814882, 2021).
pancreatic ductal adenocarcinoma (7 papers, 2015 to 2024). An infiltrating adenocarcinoma that arises from the epithelial cells of the pancreas. "Moreover, high expression of IL-6 receptor (IL-6R) was confirmed in PCCs and the activation of IL-6R-related pathway in tumor cells was associated with a poor outcome in resected pancreatic ductal adenocarcinoma." (PMID 25609203, 2015). "IL-6-induced STAT3 phosphorylation in pancreatic ductal adenocarcinoma (PDAC) was suppressed by blocking IL-6R leading to the attenuation of STAT3 activation in TME toward enhanced sensitivity of cancer cells to chemotherapy." (PMID 36091805, 2022). "In pancreatic ductal adenocarcinoma, application of IL6R blocking antibodies through inhibiting IL6 signaling could shift the tumor microenvironment from a chemoresistant state to a chemosensitive state, which was accompanied with reduced STAT3 activation." (PMID 33714953, 2021).